FLT3 (fms related receptor tyrosine kinase 3)
Diseases named in the same sentence as FLT3 in open-access papers (continued):
Sharing a sentence is not in itself a finding about the gene and the disease.
acute myeloid leukemia (continued). "FLT3 is an RTK that drives the development of acute myeloid leukemia (AML) and is closely related to other hematopoietic RTKs including PDGFR, M-CSFR, and c-KIT." (PMID 36991452, 2023). "Fms-like tyrosine kinase (FLT3) is a receptor tyrosine kinase that plays a role in the pathogenesis of acute myeloid leukemia (AML)." (PMID 36015192, 2022). "(E) Model of ATM and mTOR-dependent survival of FLT3-ITD acute myeloid leukemia (AML) cells following FLT3 inhibition in BM microenvironment." (PMID 36259537, 2022). "FLT3 is receptor tyrosine kinase expressed on hematopoietic cells as well as acute myeloid leukemia (AML) cells, regulating cell survival and proliferation." (PMID 35337118, 2022). "Bone marrow (BM) microenvironment substantially limits downregulation of mTOR and MYC pathway in FLT3-ITD acute myeloid leukemia (AML) cells upon FLT3 inhibition in vitro and in vivo." (PMID 36259537, 2022). "This review focuses on current CAR T-cell research and clinical trials specifically targeting the FLT3 antigen to treat acute myeloid leukemia (AML)." (PMID 36289703, 2022). "DBPR114 was initially developed as a dual FLT3/AURK multikinase inhibitor for the treatment of FLT3 internal tandem duplication alteration-positive acute myeloid leukemia (AML) tumors and FLT3 wild-type AML tumors." (PMID 35062934, 2022). "Both overexpression and overactive mutations of FLT3 have been implicated in different diseases, prominently in acute myeloid leukemia (AML), of which one-third of patients carry FLT3 mutants that correlated with poor prognosis." (PMID 35269825, 2022). "Internal tandem duplication (ITD) in the Fms-related receptor tyrosine kinase 3 (FLT3) gene is found in approximately 20 to 30% of cases of normal karyotype acute myeloid leukemia (AML)." (PMID 35081962, 2022). "In addition, JAK2/FLT3 dual inhibitors could provide better therapeutic option for acute myeloid leukemia." (PMID 35631587, 2022). "FLT3 ITD and TKD mutations occur in 20% and 10% of Acute Myeloid Leukemia (AML), respectively, and they represent the target of the first approved anti-leukemic therapies in the 2000s." (PMID 36077850, 2022). "The prognostic significance of the length of internal tandem duplication (ITD) insertions in mutant FLT3 genes in acute myeloid leukemia (AML) is controversial." (PMID 35741439, 2022). "They conducted an eight-chip study of MOLM-13 cells [an acute myeloid leukemia (AML) cell line] exposed to different concentrations of the FLT3 inhibitor quizartinib to investigate the drug effects on cell growth." (PMID 36131323, 2022). "Moreover, the dual inhibition of JAK2 and FLT3 could also provide therapeutic option in the treatment of acute myelogenous leukemia and myeloproliferative neoplasms." (PMID 35631587, 2022). "Internal tandem duplication (ITD) of the fms-like tyrosine like kinase 3 (FLT3) receptor tyrosine kinase is present in acute myeloid leukemia (AML) cells of 30 percent of patients, resulting in constitutive and aberrant FLT3 signaling." (PMID 34504649, 2021). "HSN608 is a novel and potent inhibitor of the Fms-like tyrosine kinase 3 (FLT-3), a protein overexpressed in patients with acute myeloid leukemia (AML)." (PMID 34834084, 2021). "Internal tandem duplications (ITD) mutation, the most frequent mutation in the juxtamembrane domain of the FMS-like tyrosine kinase 3 (FLT3) gene, was found in almost 20% of all acute myeloid leukemia (AML) patients." (PMID 34820336, 2021). "PRI-724 potently disrupts β-catenin interaction with CBP, thereby inhibiting acute myeloid leukemia (AML) cells and synergizing with FLT3 inhibition in FLT3-mutant AML." (PMID 34445128, 2021).
acute myeloid leukemia (continued). "A study by the Austrian-German Acute Myeloid Leukemia Study Group (AGAMLS) of FLT3-ITD+ AML patients who were treated with midostaurin and either relapsed or had refractory response, showed loss of FLT3-ITD mutation in nearly half of the patients." (PMID 34680203, 2021). "Gilteritinib is an ATP-competitive tyrosine multi-kinase inhibitor that has been approved for treating relapsed or refractory Fms-like tyrosine kinase 3 (FLT3)-positive acute myeloid leukemia (AML)." (PMID 35004700, 2021). "Activating mutations of FMS-like tyrosine kinase 3 (FLT3) have been shown to drive the initiation and progression of acute myeloid leukemia (AML)." (PMID 33834022, 2021). "Fms-related tyrosine kinase 3 (FLT3) receptor serves as a prognostic marker and therapeutic target in acute myeloid leukemia (AML)." (PMID 33531064, 2021). "FLT3 and dual Aurora B/FLT3 inhibitors have shown relevance in the search for promising new anticancer compounds, mainly for acute myeloid leukemia (AML)." (PMID 32283751, 2020). "AML patients carrying FLT3-ITD have a poor prognosis as indicated in the NCCN guidelines Version 1.2016 Acute Myeloid Leukemia." (PMID 32948748, 2020). "FMS like tyrosine kinase 3 (FLT3) is a receptor tyrosine kinase expressed by acute myeloid leukemia (AML) cells in 70% to 90% of patients." (PMID 32215183, 2020). "Midostaurin is a novel agent for FLT3-TKD/-ITDmut-acute myeloid leukemia (AML) and metabolized via cytochrome P450 3A4 (CYP3A4)." (PMID 32514626, 2020). "Quizartinib, a potent, selective FMS-like tyrosine kinase 3 (FLT3) inhibitor, is currently in phase 3 development for patients with FLT3–internal tandem duplication-mutated acute myeloid leukemia (AML)." (PMID 31385001, 2019). "In hematologic malignancy, 70% to 100% increased expression of FLT3 in acute myeloid leukemia (AML) and acute lymphoblastic leukemia (ALL) is reported previously." (PMID 31565544, 2019). "Signal transducers and activators of transcription 5A and 5B (STAT5A and STAT5B) are crucial downstream effectors of tyrosine kinase oncogenes (TKO) such as BCR-ABL in chronic myeloid leukemia (CML) and FLT3-ITD in acute myeloid leukemia (AML)." (PMID 31861239, 2019). "Internal tandem duplication of FLT3 juxtamembrane domain (FLT3-ITD)-positive acute myeloid leukemia (AML) leads to poor clinical outcomes after chemotherapy." (PMID 30862120, 2019). "Internal tandem duplications (ITD) within the juxtamembrane domain of FMS-like tyrosine kinase 3 (FLT3) represent a poor prognostic indicator in acute myeloid leukemia (AML)." (PMID 30947742, 2019). "FMS-like receptor tyrosine kinase-3 (FLT3) belongs to the family of receptor tyrosine kinase (RTK), and the FLT3 mutation is observed in 1/3 of all acute myeloid leukemia (AML) patients." (PMID 29416667, 2018). "Fms-like tyrosine kinase 3 internal tandem duplication (FLT3-ITD) is one of the most common genetic lesions in acute myeloid leukemia patients (AML)." (PMID 29682194, 2018). "Fms-like tyrosine kinase 3 (FLT3) with internal tandem duplications (ITD) is a major oncoprotein in acute myeloid leukemia (AML), and confers an unfavorable prognosis." (PMID 28460451, 2017). "Acute myeloid leukemia (AML) with internal tandem duplications in the FLT3 tyrosine kinase (FLT3-ITD) remains a disease with dismal prognosis." (PMID 29312564, 2017). "Constitutively activating internal tandem duplication (ITD) alterations of the receptor tyrosine kinase FLT3 (Fms-like tyrosine kinase 3) are common in acute myeloid leukemia (AML) and classifies FLT3 as an attractive therapeutic target." (PMID 28450419, 2017). "USP22 can deubiquitinate Sirt1 and enhance its stability through c-MYC-related network, leading to FLT3 tyrosine kinase inhibitors (TKIs) resistance in acute myeloid leukemia (AML)." (PMID 28567015, 2017).
acute myeloid leukemia (continued). "Clinical trial data show that the residual disease can persist in the bone marrow of patients with acute myeloid leukemia (AML) expressing oncogenic FLT3 that are treated with the small molecule inhibitor, midostaurin." (PMID 29299123, 2017). "In this study, we evaluated the frequency of FMS-like tyrosine kinase 3 (FLT3-ITD and FLT3-TKD) and nucleophosmin (NPM1) mutations in Iranian patients with cytogenetically normal acute myeloid leukemia (CN-AML)." (PMID 28294102, 2017). "Blast cells of most cases of acute myeloid leukemia (AML) express Flt3 and Flt3L has a strong stimulatory effect on these cells, enhancing colony growth when other cytokines are present at suboptimal levels." (PMID 28498310, 2017). "FLT3 is a type III receptor tyrosine kinase, which is mutated in more than 30% of acute myeloid leukemia (AML) and the most common mutations is the internal tandem duplication (ITD) mutations." (PMID 26895103, 2016). "FLT3 is expressed in normal hematopoietic progenitor cells, in most acute myeloid leukemia's (AML), and a smaller subset of B-cell acute lymphoblastic leukemia (ALL), blast crisis chronic myeloid leukemia (CML) and T-cell ALL." (PMID 27329844, 2016). "Therapy directed against oncogenic FLT3 has been shown to induce response in patients with acute myeloid leukemia (AML), but these responses are almost always transient." (PMID 26999641, 2016). "Mutations in the FMS-related tyrosine kinase 3 (FLT3) gene represent one of the most frequent and clinically challenging event in Acute Myeloid Leukemia (AML), occurring in the 25% of newly diagnosed cases." (PMID 26384303, 2015). "Furthermore, the patient was found to harbor FLT3-ITD mutation, which might collaborated with CHD1-RUNX1 in the development of acute myeloid leukemia." (PMID 25879624, 2015). "Gain-of-function mutations of FLT3 (FLT3-ITD), comprises up to 30% of normal karyotype acute myeloid leukemia (AML) and is associated with an adverse prognosis." (PMID 26450903, 2015). "An internal tandem duplication of the FLT3 gene (FLT3/ITD) is recurrent in acute myeloid leukemia (AML) and myelodysplastic syndrome (MDS) with frequencies of 20 and 3-15%, respectively." (PMID 24597945, 2014). "D-type cyclins have also been shown to be downstream effectors of Flt3 in acute myeloid leukemia (AML)." (PMID 24919854, 2014). "Mutations in FLT3 and KIT have been shown to play a role in the development of malignancies such as acute myeloid leukemia (AML) and advanced systemic mastocytosis (ASM)." (PMID 24085261, 2013). "For example, in acute myeloid leukemia (AML), recurrent mutations that portend for a high risk of relapse after conventional treatment include those with chromosome 7 abnormalities, chromosome 5 abnormalities, complex karyotypic abnormalities, and mutations in the FLT3 gene." (PMID 22312362, 2012). "Flt3, a key regulator of hematopoietic cell growth, is frequently deregulated in AML (acute myeloid leukemia)." (PMID 22514634, 2012). "The development of targeted treatments, including inhibitors of BCL-2, FLT3, IDH1/2, and menin, has significantly expanded the therapeutic landscape of acute myeloid leukemia (AML), offering more personalized and molecularly driven treatment approaches." (PMID 41899095, 2026). "In acute myeloid leukemia (AML), the insertion site of internal tandem duplications (ITDs) within the FLT3 gene critically determines the sensitivity to tyrosine kinase inhibitors (TKIs)." (PMID 42265194, 2026). "A 59-year-old woman with persistent lower-leg erythema and pain, initially misdiagnosed as cellulitis, was later diagnosed with erythema nodosum (EN) and acute myeloid leukemia (AML), French-American-British (FAB) subtype M2, carrying a FLT3-internal tandem duplication (ITD) mutation." (PMID 40091927, 2025).
acute myeloid leukemia (continued). "Despite initial success with FLT3 inhibitors (FLT3is), outcomes for FLT3-ITD acute myeloid leukemia (AML) patients remain unsatisfactory, underscoring the need for more effective treatment options." (PMID 39955584, 2025). "In acute myeloid leukemia (AML), the targeting of the FLT3 and BCL-2 pathways has indirectly diminished leukemic stem cells, leading to significant enhancements in survival with medicines like venetoclax." (PMID 41439922, 2025). "Additionally, in FLT3-ITD-positive acute myeloid leukemia (AML) cells, PDP1 facilitates cellular respiration, even under hypoxic conditions." (PMID 39776803, 2025). "Here, we revealed that the oncogenic activation of FLT3/ITD induced upregulation of target genes of sterol regulatory element-binding proteins (SREBPs) in vivo and in acute myeloid leukemia patients." (PMID 40263296, 2025). "In agreement with previous studies, USP10 acts as an oncoprotein in hepatocellular carcinoma, esophageal squamous cell carcinoma, glioblastoma, and acute myeloid leukemia through the stabilization of YAP, ANLN, RUNX1, and FLT3." (PMID 40605431, 2025). "FMS-like tyrosine kinase 3 (FLT3) is a transmembrane receptor tyrosine kinase highly expressed in acute myeloid leukemia (AML), particularly in cases harboring internal tandem duplication (FLT3-ITD) or tyrosine kinase domain (FLT3-TKD) mutations, which occur in approximately 30% of patients." (PMID 41280924, 2025). "In Acute Myeloid Leukemias (AML), FLT3 inhibitors enhance the sensitivity of FLT3-mutant AML cells to lipid oxidative stress by inhibiting the C/EBPα/SCD axis, thereby inducing ferroptosis." (PMID 40093329, 2025). "Acute myeloid leukemia (AML), the dominant acute leukemia in adults, has shown survival gains with FLT3/IDH inhibitors and Bcl-2 antagonists; however, resistance and relapse limit the 5-year survival to approximately 30%." (PMID 40690460, 2025). "This retrospective cohort study assessed adult patients with acute myeloid leukemia (AML) who received FLT3 and/or NPM1 testing treated at any Veterans Health Administration (VHA) facility or at Vanderbilt University Medical Center (VUMC) between January 2006 and December 2016." (PMID 41332821, 2025). "The standard-of-care treatment for patients with acute myeloid leukemia (AML) is being challenged by new classes of targeted therapies, including FLT3, IDH and BCL2 inhibitors." (PMID 38783160, 2024). "In acute myeloid leukemia (AML), the frequency of FLT3-ITD and TKD ranges from 9.7% to 16.5% and from 4.3% to 11.3%, respectively." (PMID 39273530, 2024). "Differentiation syndrome (DS) is associated with a higher risk of coagulopathy and hemorrhage, which can be seen in patients with APL undergoing induction therapy with all-trans retinoic acid (ATRA) and acute myeloid leukemia (AML) on IDH and FLT3 inhibitors." (PMID 39202529, 2024). "In acute myeloid leukemia (AML), FLT3 has become a promising therapeutic target, as FLT3 TKD- and ITD-positive AML account for almost one-third of all cases." (PMID 39518156, 2024). "FLT3-ITD is a type of poor prognostic factors in acute myeloid leukemia (AML) disease." (PMID 39015500, 2024). "AML: acute myeloid leukemia; ALL: acute lymphoblastic leukemia; MRD: minimal residual disease; NPM1: nucleophosmin 1; FLT3: Fms-like tyrosine kinase-3; CNS: central nervous system; SCT: Stem cell transplantation; CR: complete remission." (PMID 39310608, 2024). "In this study, we observed that pediatric patients with acute myeloid leukemia (AML) exhibiting co-expression of NUP98-NSD1, FLT3-ITD, and WT1 in our cohort showed a lower response rate to chemotherapy." (PMID 39068406, 2024).
acute myeloid leukemia (continued). "ABT869 exhibits anti-proliferative effects in multiple cancers with FMS-like tyrosine kinase 3–internal tandem duplication (FLT3-ITD) (e.g., acute myeloid leukemia) by inhibiting phosphorylation of FLT3, STAT5, and ERK, consequently inducing apoptosis." (PMID 37264282, 2023). "USP10 acts as a cancer-promoting factor in liver cancer and acute myeloid leukemia through stabilization of YAP and FLT3." (PMID 36526897, 2023). "FLT3, when activated by an internal tandem duplication (FLT3-ITD), activates glucose consumption in acute myeloid leukemia cells." (PMID 36697489, 2023). "Post-transplant maintenance in acute myeloid leukemia (AML) has long been debated with recent implementation by transplant centers, mostly with the use of hypomethylating agents (HMAs) and FLT3 inhibitors." (PMID 36595164, 2023). "Class III RTKs, which include c-Kit, CSF1R, FLT3, and platelet-derived growth factor receptors (PDGFR), have been discovered to have a major effect on leukemogenesis and transformation into acute myeloid leukemia." (PMID 37047003, 2023). "Notably, the most common genetic alteration observed in acute myeloid leukemia (AML) patients is in Fms-like tyrosine kinase 3 (FLT3), a receptor for tyrosine kinase." (PMID 38078003, 2023). "In the context of acute myeloid leukemia (AML), FLT3 takes on an even more pronounced role." (PMID 38001685, 2023). "This retrospective study investigated outcomes of 404 patients with relapsed/refractory (R/R) FMS-like tyrosine kinase 3 (FLT3)-internal tandem duplication (ITD) acute myeloid leukemia (AML) enrolled in the PETHEMA registry, pre-approval of tyrosine kinase inhibitors." (PMID 35681796, 2022). "FLT3–ITD results in a poor prognosis in terms of overall survival (OS) and relapse-free survival (RFS) in acute myeloid leukemia (AML)." (PMID 36497281, 2022). "FMS-like tyrosine kinase 3 (FLT3) is the most frequent single-gene mutation in acute myeloid leukemia: about 25% of adult patients with AML have FLT3 internal tandem duplication (FLT3-ITD) and 10% have FLT3 tyrosine kinase domain (FLT3-TKD) point mutations or deletions." (PMID 36530990, 2022). "Nucleophosmin‐1 (NPM1) mutations in acute myeloid leukemia (AML) confer a survival advantage in the absence of FLT3‐internal tandem duplication (FLT3‐ITD)." (PMID 35048553, 2022). "In acute myeloid leukemia (AML), RIPK3 signaling might be epigenetically repressed in leukemic cells isolated from a subgroup of AML patients such as AML with RUNX1-ETO or FLT3-ITD mutations." (PMID 35561683, 2022). "In contrast, the overexpression of FLT3 protein has been found in leukemic blood cells, especially in AML (acute myeloblastic leukemia) and B-cell acute lymphoid leukemia (B cell ALL)." (PMID 36297550, 2022). "Generally, FLT3 is well studied in acute myeloid leukemia (AML)." (PMID 36159964, 2022). "Sorafenib, a multi-kinase inhibitor with N,N-diphenyl urea structure that can inhibit the activity of c-RAF, b-RAF, c-KIT, FLT3, PDGFR-α/β, and VEGFR-1/2/3 is usually used in tumor treatment, especially in acute myeloid leukemia (AML) clinical trials." (PMID 36558930, 2022). "Mutations in the activation loop of the tyrosine kinase domain (TKD1) of FLT3 are present in up to 30% of patients with acute myeloid leukemia (AML), and FLT3 has been utilized as a potential target for kinase inhibitor therapy." (PMID 35454900, 2022). "Acute myeloid leukemia (AML) is a molecularly heterogenous hematological malignancy, with one of the most common mutations being internal tandem duplication (ITD) of the juxtamembrane domain of the fms-like tyrosine kinase receptor-3 (FLT3)." (PMID 35453402, 2022). "Furthermore, there is also clinicopathological relevance to MCT dogs carrying FLT3-ITD mutations, showing a tendency toward leukocytosis due to neutrophilia, and resembling human acute myeloid leukemia (AML) with FLT3-ITD mutations." (PMID 36072760, 2022).